IL33 (interleukin 33)
Diseases named in the same sentence as IL33 in open-access papers (continued):
Sharing a sentence is not in itself a finding about the gene and the disease.
tumor (continued). "Tumor derived IL-33 is capable of inducing tumor angiogenesis by activating EC." (PMID 31293586, 2019). "Moreover, the gradual upregulation of ST2 on tumor-isolated CD4+ FOXP3+ Tregs during intestinal tumorigenesis suggested an immune regulatory function of IL-33 for this disease." (PMID 31165767, 2019). "Moreover, we found that frequencies of ST2+ Tregs gradually increase during CRC development to correlate with tumor scores and IL-33 expression." (PMID 31165767, 2019). "Administration of exogenous IL-33 has also been shown to have potent tumor protective effects." (PMID 31231372, 2019). "IL-33 EO induced rapid apoptosis of tumor cells with greater efficiency than IL-5 EO." (PMID 31717819, 2019). "Lnc-CAF up-regulates IL-33 expression to reprogram CAFs, promoting tumor development." (PMID 31448238, 2019). "IL-33 is an epithelial-derived “alarmin” playing multiple functions in Th2-related immunopathologies and recently implied in cancer immunity, exerting pro- or anti-tumoral activities, depending on the tumor type and microenvironmental factors." (PMID 31717819, 2019). "The distribution of ST2L+ effector CD8high and transitional or memory CD8low T cells in tumor tissue might therefore reveal essential findings contributing to the understanding of the IL-33/ST2L axis in cancer immunity." (PMID 31396219, 2019). "One notable exception is the use of IL-33 blockade in tumor microenvironments." (PMID 30949175, 2019). "Differences between healthy subjects and tumor patients might not only occur regarding the systemic activity and function of IL-33, but also with respect to the IL-33-dependent differentiation of pro- and anti-inflammatory CD8high and CD8low T cells." (PMID 31396219, 2019). "However, predicting the outcome of IL-33/ST2 signaling in malignancies remains uncertain with both tumor promoting as well as tumor restricting activities being reported in knockout mouse models." (PMID 31227713, 2019). "A putative anti-tumor role of ILC2s has been proposed in a subcutaneous lymphoma mouse model, where sustained production of IL-33 induced the upregulation of CXCR2 on EL4 thymoma cells, the expansion of ILC2s and the concomitant production of CXCR2 ligands (CXCLs)." (PMID 31849977, 2019). "These events led to eosinophil degranulation, as demonstrated by TEM analysis, showing emptying granules in IL-33 EO adjoining tumor cells, and by up-regulation of surface CD63, an intracellular granule marker that translocates to the cell membrane as a result of degranulation." (PMID 31717819, 2019). "Conversely, reduced levels of serum IL-33 is observed in CRC patients compared with healthy individuals and decreased expression of ST2L, the transmembrane isoform of the ST2 receptor, in CRC tumors is associated with higher tumor grade and worse prognosis." (PMID 32010138, 2019). "Increasing evidence indicates that the IL-33/ST2 axis plays a role in tumor immunity." (PMID 31500217, 2019). "Furthermore, time-lapse video microscopy revealed that IL-33-activated EO had higher propensity to migrate towards and interact with tumor cells, in comparison with IL-5 EO." (PMID 31717819, 2019). "Notably, polarized degranulation in IL-33 activated eosinophils upon contact with target tumor cells was clearly visible by TEM analysis." (PMID 31717819, 2019). "Necroptosis, IL33 levels, and neutrophil infiltration together or through independent mechanisms could be leading to a pro-tumor environment." (PMID 30775178, 2019). "Similarly, a recent account revealed that the tumor-specific release of IL-33 can promote the accumulation of TREG cells at the site where they contribute to tumor growth and immune evasion." (PMID 30949175, 2019). "IL-33 could inhibit tumor progression by recruiting CD8+ T, natural killers (NKs), eosinophils, and dendritic cells, and by the induction of IFN-γ." (PMID 31130612, 2019). "On the other hand, tumor expression of IL-33 may induce the production of chemokines that recruit eosinophils." (PMID 31717819, 2019).
tumor (continued). "This significant serum-pleural IL-33 difference of the malignant group could be explained by that the tumor development results in down-regulation of IL-33 in epithelial cells but up-regulation of IL-33 in the tumor stroma and serum." (PMID 31238901, 2019). "Both markers are moderately correlated (Spearman r = 0.5, p = 0.01), suggesting that IL-33 and ST2 variants present in the tumor are related to fibroblast activation and could potentiate the desmoplastic reaction of the tumor." (PMID 31281317, 2019). "IL-1 family member IL-33 exerts a variety of immune activating and regulating properties and has recently been proposed as a prognostic biomarker for cancer diseases, although its precise role in tumor immunity is unclear." (PMID 31396219, 2019). "Indeed, CLSM observations showed substantial polarization of granzyme-B and cationic proteins in IL-33 EO-tumor cell conjugates." (PMID 31717819, 2019). "Thus, IL-33 recruits tumor-infiltrating eosinophils indirectly, via stimulation of chemokine production at least in part by tumor cells." (PMID 31717819, 2019). "The role of IL-33 in tumor immunity is still highly controversial." (PMID 31396219, 2019). "This suggests that one of the direct mechanisms by which IL-33 could be favoring tumor progression in CRC is through desmoplasia activation." (PMID 31281317, 2019). "The broad expression of IL-33 in cancers and the pro-tumor functions of Th2 and Tregs suggest ILC2s may facilitate the tumor growth by helping the installation of a pro-tumor immunity." (PMID 31024531, 2019). "Therefore, we were interested in evaluating the protein levels and distribution of IL-33/ST2 according to tumor location." (PMID 31281317, 2019). "IL-33 is a cytokine involved in the regulation of not only antitumor immunity but tumor growth." (PMID 31652497, 2019). "IL-33 favors tumor tolerance through inducing M2 macrophages, activating MDSCs, and Tregs." (PMID 31681327, 2019). "Importantly, IL-33 is correlated with tumour migration and some growth factors as well as chemokine expression regulation." (PMID 31889095, 2019). "Its systemic role in the activation and recruitment of cytotoxic T cells to tumor tissue remains unclear, as bioactivity of IL-33 detected in blood by ELISA is missing." (PMID 31396219, 2019). "To obtain insights into the changes in gene expression that take place as a result of IL-33 expression by tumour cells, we conducted a pathway-focused gene expression analysis, using the “Mouse Cancer Inflammation & Immunity Crosstalk RT2 Profiler PCR Array” (Qiagen)." (PMID 29440650, 2018). "Thus, IL-33 targeted both tumor cells and macrophages to confer a novel immune-mediated mechanism to promote CRC malignancy." (PMID 30205617, 2018). "Thus, IL-33 can promote type 1 immunity against cancer in the setting where a cancer therapy induces tumor cell death and release of large amounts of IL-33." (PMID 29499051, 2018). "To test whether the spread of the tumour cells to the lungs may alter the level of local lung ILC2s, we quantified lung ILC2s from mice bearing either metastatic A9+IL-33 or primary TC1 tumours." (PMID 29440650, 2018). "In elegant studies using a sporadic model of non-inflammatory CRC, loss of ST2 enhanced tumor development while administration of IL-33 reduced growth of CRC allografts." (PMID 30205617, 2018). "Overall, our data supports the conclusion that the high level of IL-33 provides immune stimulatory microenvironment that is directly correlated with the presence of the innate and adaptive immune cell subsets that mediate protective anti-tumour immunity." (PMID 29440650, 2018). "Interleukin (IL)‐33/ST2 pathway plays crucial roles in tumour growth and metastasis." (PMID 29797504, 2018). "Increasing evidences indicate that IL-33 may have opposing functions, promoting, or dampening tumor immunity, depending on the tumor type, site of expression, and local concentration." (PMID 30483263, 2018).
tumor (continued). "Clinical therapeutics such as radiotherapy and chemotherapy could induce IL-33 expressions in tumor tissue of clinical patients, suggesting clinical managements as critical factors in determining IL-33 expressions." (PMID 29568370, 2018). "These contrasting results suggest that IL-33 may exert opposing effects on NK cells within the tumor microenvironment depending on the levels of IL-33 expressed and on the primary target cells." (PMID 30483263, 2018). "Taken together, these results suggest that the IL-33/ST2 axis may enhance the antitumor immunity by promoting the recruitment recruitment of type 1-polarized CD8+ T cells into tumor lesions in STS." (PMID 29896199, 2018). "Depletion of eosinophils completely abolished the anti-tumor effects of IL-33 administration." (PMID 30483263, 2018). "Mechanistically, IL-33 facilitated tumor development in vivo through the up regulation of IL-6." (PMID 30205617, 2018). "We found that components of the antigen processing pathway (H2-K1, β2 m) were elevated in A9 metastatic tumours expressing IL-33, whereas the expression of immunosuppressive factors (IL-10, Ptgs2) were diminished, thereby altering the tumour microenvironment toward immune responsiveness." (PMID 29440650, 2018). "Tumoral expression of IL-33 could inhibit tumor growth and modify tumor microenvironment through CD8 T and NK cells in mice bearing B16 cells and 4T1 cells." (PMID 29568370, 2018). "Put together, it is proposed that IL-33 might exert the anti-cancer activities of suppressing tumor growth under certain circumstances." (PMID 30619376, 2018). "IL-33 could be released by damaged or dead tumor cells and act on immune cells that express ST2 in a paracrine or autocrine manner." (PMID 29896199, 2018). "Moreover, exogenous administration of IL-33 to WT 4T1 tumor-bearing mice decreased NK cell activation and cytotoxicity and promoted tumor progression, thus suggesting a detrimental role for IL-33 in NK cell-dependent anti-tumor responses." (PMID 30483263, 2018). "These evidences indicate that IL-33 may promote or halt MDSCs expansion depending on the tumor type." (PMID 30483263, 2018). "Remodeling tumor stroma and pro-angiogenesis: IL-33 markedly stimulates myofibroblasts to produce several types of extracellular matrix components including MMP2, MMP9, and growth factors associated with CRC tumor growth, progression and metastasis." (PMID 30547011, 2018). "Different mechanisms have been proposed to mediate the pro-tumor or anti-tumor activity of IL-33, and further studies will be needed to determine exact effects of IL-33 and whether these findings can be generalised to different types of tumors." (PMID 30112116, 2018). "Based on these clues, we hypothesized that since ILC2s are developmentally and functionally dependent on IL-33, ILC2s may have an undescribed role in promoting and mediating immune responses against tumours." (PMID 29440650, 2018). "Knockdown of IL-33 is likely to correct this problem and resistance to tamoxifen-induced tumor growth inhibition could therefore be reversed." (PMID 30619376, 2018). "We found exogenously administered recombinant mouse interleukin 33 promoted tumorsize and induced tumor-infiltrating ST2L+ regulatory T cells in tumor-bearingmice while neutralizing interleukin-33 or ST2L inhibited tumor size and decreasedST2L+ regulatory T cells." (PMID 29950152, 2018). "Because recent studies have shown that IL-33 enhances the function of effector NK cells, we next considered whether ST2 deficiency affects NK cytotoxicity in our SCC tumor model." (PMID 30112116, 2018). "Hence, CAFs overexpressing IL-33 promote the induction of epithelial-to-mesenchymal trans-differentiation, eventually leading to tumor progression and poor prognosis." (PMID 30483263, 2018). "Furthermore, the spread of metastatic A9 tumour cells was higher when compared to metastatic A9+IL-33, in both WT and RORα−/− bone marrow chimeric mouse models." (PMID 29440650, 2018).
tumor (continued). "Furthermore, B16 and 4T1 tumor cells overexpressing IL-33 implanted into syngeneic mice induced IFN-γ+ NK cells in tumor tissue that mediated IL-33 anti-tumoral effect." (PMID 30483263, 2018). "Alongside its pro-tumorigenic role, IL-33 can also behave as a tumor suppressor." (PMID 30416507, 2018). "Moreover, IL-33 blockade reduced accumulation of Treg cells in tumor microenvironment and inhibited tumor growth in a preclinical model of human non-small-cell lung cancer (NSCLC) xenografts." (PMID 30483263, 2018). "Therapeutically targeting pericytes to prevent angiogenesis and IL-33 production might thus be used to restrict tumour growth." (PMID 30097696, 2018). "In cancer immunology, IL-33 inhibits tumor growth through activation of CD8+ T and NK cells." (PMID 30108595, 2018). "For example, IL-33 activates NK cells which could direct kill tumor cells, and could also induce the release of anti-tumor cytokines, such as IFN-γ and TNF-α." (PMID 30112116, 2018). "Using reciprocal bone marrow chimeras, simultaneous loss of IL-33 signaling in both radioresistant non-hematopoietic and radiosensitive hematopoietic compartments resulted in increased tumor burden." (PMID 30205617, 2018). "Large bodies of evidence indicate that IL-33 has a potent anti-tumor function in many cancers." (PMID 29499051, 2018). "Thus, Lnc-CAF/IL-33 promotes OSCC development by modifying the TME through reprogramming of NFs to CAFs in the tumor stroma." (PMID 30205617, 2018). "Furthermore, in mouse tumor xenografts IL-33 was shown to promote metastasis through recruitment of M2-like TAMs." (PMID 30483263, 2018). "Moreover, accumulation of CD8+T cells in tumor beds of A9+IL-33 derived tumors were higher as compared to A9+vector and TC1+vector derived tumors." (PMID 30205617, 2018). "And the level of IL-33 protein was inversely correlated with tumor grade and size." (PMID 29499051, 2018). "Thus, while studying the IL-33 involvement in anti-cancer immunity, it’s important to specify the tumour type and clinical stage of the disease." (PMID 29440650, 2018). "The combined use of dectin-1-activated DCs and IL-33 may present a new effective modality of DC-based vaccines in tumor immunotherapy." (PMID 30108595, 2018). "Moreover, the level of IL-33 protein has been inversely correlated with tumor grade and size in patients with pulmonary adenocarcinoma, showing an association of low IL-33 expression level with a poor prognosis." (PMID 30416507, 2018). "Moreover, the increased number of immune cells within primary tumours or metastatic IL-33-expressing tumours supports the conclusion that tumour-infiltrating innate and adaptive immune cells can overcome immune-deficiency in metastatic tumours in vivo." (PMID 29440650, 2018). "A significant decrease in the ILC2 number in metastatic tumours versus primary, or IL-33-complemented tumours, was observed, providing further evidence that ILC2s could contribute to tumour immune surveillance." (PMID 29440650, 2018). "However, in Lewis lung carcinoma, the transgenic expression of IL-33 inhibited tumor growth and metastasis in mice." (PMID 30112116, 2018). "Loss of IL-33 or ST2 by genetic knockout inhibited tumor growth, induced apoptosis, and suppressed angiogenesis in ApcMin/+ polyps resulting in decreased tumor burden and size." (PMID 30205617, 2018). "The anti-tumor functions of IL-33 also depend on infiltrated immune cells displaying TH1 responses." (PMID 30416507, 2018). "Finally, several studies have shown an important involvement of IL-33 in several types of cancer with pro or anti-tumorigenic functions depending on the immune status of the tumor." (PMID 30416507, 2018). "These pro-tumor effects of IL-33 are mainly mediated by IL-33 receptor ST2 (also known as IL-1RL1)." (PMID 30547011, 2018).
tumor (continued). "Depending on the tumor context, IL-33 produced in the TME can activate diverse immune cells which are able to promote a pro-tumor effect such as TAM, MDSC, fibroblasts, mast cells, Treg and DC, or to prevent tumor development such as NK cells, CD8+ T cells, iNKT, ILC2, TH9, and TH17." (PMID 30416507, 2018). "Thus, studies regarding the role of IL-33 in tumor development has attracted much attention and evidence is accumulating." (PMID 30559604, 2018). "Moreover, clinical studies have shown that increased expression of IL-33 links to the tumor invasion, metastasis and prognosis in patients with cancers." (PMID 30559604, 2018). "Little is known about the effects of IL-33 on neutrophils in tumor immunity." (PMID 30483263, 2018). "Further studies are needed to better understand the mechanisms by which IL-33 may enhance tumor burden in these patients." (PMID 30205617, 2018). "Similarly, immunization with CurDCs plus IL-33 significantly slowed MPC-11 tumor growth as compared to CurDC immunization, whereas IL-33 had marginal effects on BMDC-induced antitumor efficacy." (PMID 30108595, 2018). "However, if IL-33 can have a pro-tumor effect by directly targeting cancer cells, the tumor suppressor functions displayed by IL-33 are indirectly promulgated by immune surveillance as we will show hereafter." (PMID 30416507, 2018). "On the whole, these results suggest that IL-33 depending on the context can stimulate DC antigen presentation and, thus, anti-tumor immune responses, or induce tolerogenic features, thus supporting tumor growth." (PMID 30483263, 2018). "We found that the higher expressed IL-33 intumor-bearing mice promoted the tumor size, increased ST2L+Treg cells, andantiinflammatory cytokines production, while neutralization of IL-33 inhibited tumor sizedecreased ST2L+Treg cells and antiinflammatory cytokines production." (PMID 29950152, 2018). "However, further investigation should be performed to better understand the physiopathology of IL-33 during tumor development." (PMID 30112116, 2018). "Thus, IL-33 is a potent pleiotropic cytokine that reverses immunosuppression in the tumor microenvironment." (PMID 29896199, 2018). "In addition, in a mouse model of DNA cancer vaccine, delivery of either full-length or mature IL-33 as an immunoadjuvant induced potent Th1 and cytotoxic T cell (CTL)-associated anti-tumor immunity and complete regression of established TC-1 tumor in mice." (PMID 30483263, 2018). "Furthermore, DC can also drive TH9 cell dependent anti-tumor responses through the expression of Ox40L when activated by IL-33 and stimulated by dectin-1 signaling." (PMID 30416507, 2018). "IL-33 promoted tumor cell proliferation and angiogenesis in wild type mice but not in ST2−/− mice." (PMID 30205617, 2018). "For example, IL-33 promotes chronic inflammation and tumour development in some models." (PMID 29587679, 2018). "TH17 cells could have an anti-tumor function with the production of pro-inflammatory cytokines or a pro-tumor role when they can acquire a regulatory phenotype with immunosuppressive properties upon IL-33 activation." (PMID 30416507, 2018). "Therefore, the results presented here, reveal a previously unappreciated ability of epithelial expressed-IL-33 to control tumor progression in the intestine through effects on both immune and epithelial cells." (PMID 28710436, 2017). "In addition, precise molecular mechanisms connecting IL-33 and tumor outgrowth, as well as immune surveillance, in NSCLC patients are unclear." (PMID 28978138, 2017). "In conclusion, elevated IL-33 signaling increases tumor development in the ApcMin/+ mice." (PMID 28710436, 2017). "Therefore, higher expression of IL-33 in tumor epithelial cells was observed in moderate- and poorly-differentiated CRC patients." (PMID 28710436, 2017). "Blocking IL-33 activity restricts tumor growth of NSCLC xenografts." (PMID 28978138, 2017).